CD4 (CD4 molecule)
Diseases named in the same sentence as CD4 in open-access papers (continued):
Sharing a sentence is not in itself a finding about the gene and the disease.
colitis (continued). "This may partly be because mTORC1 inhibition decreases the expression of IL-23R on CD4+ T cells, a receptor for cytokine (IL-23) that is required for the induction of IL-17A/IFN-γ double-positive T cells and exacerbates the clinical course in murine colitis." (PMID 23383714, 2013). "Similarly in a CD4 T cell transfer model of colitis, BTLA−/− T cells transferred into Rag−/− hosts failed to accumulate, with the reduced number of effector T cells in the recipients ultimately affecting disease progression." (PMID 24205056, 2013). "Our findings differ from the conclusions reported by Shinohara and colleagues in which they used an adoptive transfer model of colitis to show that expression of IL-7Rα on CD4+ T cells, but not on other cells (NK cells, granulocytes, macrophages, and DC), was essential for development of colitis." (PMID 23057802, 2012). "Enlargement of lymphoid organs (cervical lymph nodes and spleens) in CD4-DNTGFβRII mice was observed to be greater at 8 weeks than 14 weeks of age; however, we did not observe significant colitis or loose stools and 14-week old mice did not appear clinically dehydrated." (PMID 22194977, 2011). "None of the male or female Rag1tm1Mom mice that did not receive an intraperitoneal injection of splenic CD4+CD45RBhigh T cells from C57BL/6 WT donor mice but which were exposed to RST (as well as the FWD or HCC control conditions) showed evidence of sickness or colitis." (PMID 38255320, 2024). "Notably, APS significantly down-regulated the percentages of Th17 (CD4+CCR6+), cmTh17 (CD4+CCR7+CCR6+) and emTh17 (CD4+CCR7−CCR6+) cells and significantly up-regulated the percentages of cmTreg (CD4+CCR7+Foxp3+) and emTreg (CD4+CCR7−Foxp3+) cells in the mesenteric lymph nodes of the colitis mice." (PMID 38202824, 2024). "Moreover, by using the T cell-transfer model of colitis, we showed that the adoptive transfer of Smad7 Tg naïve CD4+ T cells, in the absence of Tregs, into naïve mice induces colitis that is more severe than that documented in mice reconstituted with wild-type T cells." (PMID 36714553, 2023). "Moreover, over-expression of Zbtb7b activated the maturation of CD4+T cells and repressed the differentiation of DP CD4+CD8+ T cells, which contributed to the production of inflammatory cytokines, such as TNF-α, IL-17, and IFN-γ, in the DSS-induced colitis model." (PMID 35761286, 2022). "Indeed, NOD2−/− recipients of lamina propria mononuclear cells (LPMC) from ethanol-treated NOD2−/− donors that had been depleted of CD4+LAP+Foxp3− cells exhibited increased TNBS-induced weight loss when compared to NOD2−/− recipients of intact LPMCs, which did not develop colitis." (PMID 36012618, 2022). "Given that activation of CD4+/CD8+ T cells and FOXP3+ Tregs usually mediates pro-inflammatory and anti-inflammatory responses, respectively, alterations in the colonic numbers of these adaptive T cells might be related to the resolution of colitis in patients with CC." (PMID 34350195, 2021). "Moreover, a high-level infiltration of CD4+ T cells and CD8+ T cells was reported in patients with severe colitis following immunotherapy, of which the former was more prevalent in those who underwent anti-CTLA-4 therapy and the latter usually occurred in anti-PD-1-induced colitis." (PMID 34992611, 2021). "Moreover, by using the T cell transfer model of colitis, it has been shown that the adoptive transfer of Smad7 Tg naïve CD4+ T cells, in the absence of Tregs, into naïve mice induces a colitis that is more severe than that documented in mice reconstituted with wild-type T cells." (PMID 33920230, 2021). "Furthermore, the reversion of CD4+ T-cell expansion in the spleen after neutrophil depletion in the TNBS+PFOS group indicates that neutrophils not only affect intestinal homeostasis, but also promote an extra-intestinal T-cell response in response to PFOS during colitis." (PMID 34792120, 2021).
colitis (continued). "In addition, the percentages of CD3e+CD4+CD25+Foxp3+ cells in the spleens of mice with DSS-induced colitis that were treated with M2c macrophage exosomes were significantly increased (13.5 ± 3%; P < 0.001) compared with PBS-treated mice with DSS-induced colitis (9.3 ± 1%)." (PMID 31749791, 2019). "However, other studies showed that ERα signaling in CD4+ T cells inhibited Th17 or Th1 mediated inflammation in mouse model of colitis, but ovarian hormones (including estrogen) had no direct effect on house-dust mite induced Th2-mediated airway inflammation in vivo." (PMID 31849948, 2019). "Since CD4 T cell-mediated colitis develops in the absence of IFNγ production and in the absence of IFNγ the CD4 T cells preferentially differentiate into Th17-like cells, we next investigated whether neutralization of excessive IL17 responses in the absence of IFNγ attenuates colonic inflammation." (PMID 29416538, 2018). "Similarly, immunodeficient mice adoptively transferred with CD4+IL-21−/− T cells develop less severe colitis, and mice treated in a prophylactic setup with a neutralizing IL-21R/Fc fusion protein or anti-IL-21 mAb are protected from both DSS and TNBS-induced colitis." (PMID 29849593, 2018). "In addition, we demonstrated in vivo that Treg cells with impaired IL-15 signalling when co-transferred with WT naive CD4+T cells into RAG2ko mice failed to prevent the development of colitis, while WT Treg co-transferred with IL-15Rαko naive CD4+ T cells efficiently protected against IBD." (PMID 26964669, 2016). "Thus, the regulation of the proliferative activity of CD4 T cells may not be the mechanism by which the CD69 on CD4 T cells plays a role in inducing colitis." (PMID 23785429, 2013). "Interestingly, HFD in the absence of colitis increased the CD4 and CD8 T cell populations." (PMID 22073943, 2011). "Interestingly, although CD4+ T cells are known to become overactivated during colitis and contribute to gut inflammation through the release of pro-inflammatory cytokines, studies have shown that T cells are not essential for colitis induction in the DSS-model." (PMID 40497975, 2025). "In summary, lamina propria CD4+ and CD8+ T cells from the colon show increased glucose uptake during acute but defective glucose consumption during chronic DSS colitis, a cellular adaptation that is not restored during remission." (PMID 41007657, 2025). "In contrast, the glucose consumption of CD4+ and CD8+ T cells was significantly reduced during chronic DSS colitis and did not normalize upon disease remission." (PMID 41007657, 2025). "Altogether, our results have shown that Piezo1cKO CD4+ T cells failed to induce naive CD4+ T-cell–induced pathology such as EAE, colitis, and GvHD in vivo." (PMID 39492686, 2025). "We found significantly increased IL-17A+ CD4+ T cells, after DDC+DSS treatment while frequencies of Foxp3+ Treg, and IFNγ+ CD4+ T cells were comparable between DDC treated mice with and without acute DSS colitis." (PMID 38510236, 2024). "Our study demonstrated the higher frequencies of CD4+, CD8+, NK1.1+, and CD8+NK1.1+ cells in IELs of colitis mice compared to controls; however, this increase was not statistically significant." (PMID 39201260, 2024). "In accordance with the higher colitis severity of this model, the numbers of IFN-γ+ and IFN-γ+ IL-17A+ CD4+ cells, but not IL-17+ or IL-10+ CD4+ T cells, in the large intestinal lamina propria were higher in LysoPS-treated mice than in control mice." (PMID 35608941, 2022). "Similar to the acute colitis experiment, primed hADSCs, but not untreated hADSCs, treatment significantly increased the proportion of CD45RA+ B cells and decreased the number of CD4+ T cells and CD43+His48Hi neutrophils in the spleen." (PMID 36076306, 2022). "Treatment with UroA significantly reduced/restored CD4+ T cell population in WT mice, but not in Cyp1a1-/- mice suggesting critical role of CYP1A1 in UroA-mediated correction of immune abnormalities in colitis." (PMID 36159798, 2022).
colitis (continued). "Percentages of IL-17A– or IFNγ-expressing CD4+ T cells were increased, whereas percentages of IL-17A– or IFNγ-expressing CD8+ T cells were not changed in mice with colitis compared with control mice." (PMID 35844584, 2022). "CD69+CD103− CD4+ TRM cells only accounted for 19.1% and 15.0% of Foxp3+ Treg cells in the colon of mice with or without DSS-induced colitis, respectively." (PMID 35844584, 2022). "Surprisingly, CD69+CD103− CD4+ TRM cells were the major source of IL-17A and IFNγ in the gut of mice with or without DSS-induced colitis." (PMID 35844584, 2022). "Flow cytometry analysis revealed that most of the CD4+ and CD8+ T cells from the colons of TIGIT−/− or WT mice without colitis did not express CD62L." (PMID 35844584, 2022). "FOXP3+ CD4+ T cells were increased in numbers but not frequencies, while RORγt+ (also known as RORC+) CD4+ T cells were increased in frequencies and numbers, in colitic mice exposed to PFOS while undergoing colitis." (PMID 34792120, 2021). "Butyrate upregulates expression of transcription factor Blimp-1 and IL-10 production in Th1 CD4+ T cells (without affecting conversion of Tregs or Th17 cells) via GPR43 and controls colitis." (PMID 33397404, 2021). "Intriguingly, the number of CD4+CD25 + cells was increased in the spleen and MLN of DSS-treated mice, while the percentage of CD4+FOXP3+ cells was decreased, suggested the absence of Treg cells in DSS-induced colitis." (PMID 33967779, 2021). "After 7-days’ administration of SSP and 5-ASA, the numbers of CD4+CXCR5+IL-10+ (Tfh10) and CD4+CXCR5+Foxp3+ (Tfr) (E5) were dramatically increased when compared with those in colitis mice without treatment." (PMID 32581849, 2020). "We therefore first compared the AMPK expression by Western blotting between BBR-treated colitis LP CD4+ T cells and non-BBR-treated colitis LP CD4+ T cells." (PMID 31417110, 2019). "While ILC3 promoted the pathogenesis of anti-CD40-induced innate colitis, targeted manipulation of ILC3 in the CD4 T cell transfer colitis model did not alter disease outcome." (PMID 29416538, 2018). "Transfer of colitogenic CD4 T cells to Rag1−/− mice depleted of ILC highlighted that CD4+ T cells, but not ILCs, are critical for induction of colitis." (PMID 29948108, 2018). "Intriguingly, in contrast to the anti-CD40 model of colitis, depletion of ILC in the Rag1−/− recipients of colitogenic CD4 T cells did not prevent induction of colonic inflammation." (PMID 29416538, 2018). "In an adoptive CD4+ T-cell transfer model of colitis, the amount of GLP-2 in colon tissue was also further decreased compared with that in normal mice or SCID mice without CD4+ T-cell adoptive transfer." (PMID 29270177, 2017). "Surprisingly, mice overexpressing Bcl-3 specifically in Treg cells (Bcl-3FoxP3OE mice) did not develop any signs of colitis probably due to the very high percentage of GFP− Foxp3+ Treg cells, which was less pronounced using CD4-Cre." (PMID 28452361, 2017). "In contrast to the acute chemical colitis models, attenuation of gut inflammation by CCR5 gene ablation, however, was due largely to the impaired infiltration of CD4+ T-cells and did not depend on changes in the CD11b+ myeloid compartment." (PMID 27492684, 2016). "The sjTREC+ fractions of mature Gαi2−/− thymocytes were similar in both the CD4+CD62L+ and CD8+CD62L+ populations, and did not significantly change during colitis development." (PMID 22590596, 2012). "In the current study, bortezomib treatment reduced the numbers of CD4+ and CD8+ T cells, but not B cells or macrophages during DSS-induced colitis." (PMID 22479648, 2012). "CD4+ T lymphocytes and non-T cells have been identified as sources of intestinal IFN-γ in different models of colitis." (PMID 18400195, 2008). "In this case, colitis may have been driven predominantly by locally activated CD8+ and CD4+ T cells and cytokine-mediated injury, rather than ongoing recruitment of new immune cells." (PMID 40726872, 2025).
colitis (continued). "Similarly, CD4+ and CD8+ T cells were reduced after sulfasalazine treatment in WT colitis mice, whereas this was not the case in WT colitis mice (p < 0.05)." (PMID 40977735, 2025). "In addition, CD4+ and CD8+ T cells exhibit increased glucose uptake during acute but defective glucose consumption during chronic DSS colitis that does not normalize during the remission phase." (PMID 41007657, 2025). "Since Treg levels are increased in DSS-induced colitis on day 8, but we wanted to focus on conventional T helper cells, we made use of the FoxP3-GFP reporter mice to analyze all non-Treg cells by gating on FoxP3-negative CD4+ T cells." (PMID 40422192, 2025). "It was hypothesized that IL-21 would be required for the optimal expression of IL-12Rβ2, but not IL-12Rβ1, in CD4+ T cells, thereby regulating a TH1-biased immune profile following colon inflammation." (PMID 38498592, 2024). "In CD4+CD25–CD45RBhi cell-induced colitis in Rag−/− mice, adoptive transfer of Cd28-ΔTreg cells resulted in more severe colitis compared to mice receiving WT Treg cells, revealing that Cd28-ΔTreg cells failed to suppress colitis." (PMID 34011962, 2021). "They demonstrated that both CD4+CD25-GITR+ and CD4+CD25+GITR+ T cells, regardless of the CD25 expression, could prevent the development of colitis, indicating CD4+CD25-GITR+ and CD4+CD25+GITR+ T cells can retain the regulatory function." (PMID 33163004, 2020). "Another variation of this experiment in the same paper, this time with Treg co-transferred with naïve CD4+CD25-CD45RBhigh T cells, showed that transfer of Dab2−/− Tregs into mice with an established colitis was not effective in reducing the severity of colitis." (PMID 33178208, 2020). "Based on the attenuated colitis shown in DSS-treated CCR7KO mice, we verified whether migration of CD4+ Tregs into the lymph node was impaired in the absence of CCR7." (PMID 26908454, 2016). "We tested this in the chronic T-cell driven T-cell transfer model in which RAG-1−/− mice lacking natural mature B and T-cells are transplanted with CD4+CD45RBhi cells, a model resembling Crohn’s disease, as well as in the acute dextran sodium sulfate (DSS) colitis model of epithelial injury." (PMID 26501315, 2015). "However, the total numbers of CD4 or CD8 SP thymocytes in Gαi2−/− mice with no/mild and moderate colitis were comparable to the numbers in wt littermates." (PMID 22590596, 2012). "Previously, we determined that CB-17 SCID mice, injected with CD4+CD25− cells containing DCregsCA I, experienced suppressed colitis, whereas those that received regulatory dendritic cells pulsed with cecal bacterial antigen depleted of CA I (DCregsCBA-CA I) experienced no colitis suppresion." (PMID 36289244, 2022). "Strikingly, FOXP3+ specific conditional knock out mice for MAF did not develop colitis and demonstrated normal levels of IL-10 in their colon, despite the incapacity of regulatory T cells lacking MAF to suppress colon inflammation in Rag1−/− mice transferred with naïve CD4+ T cells." (PMID 30992496, 2019). "After a preliminary validation of the ability of anti-LAP antibody administration to selectively deplete LP CD4+LAP+cell without affecting the % of LP CD4+Foxp3+ cells, we administered the antibody or its isotype control in two groups of mice, before the induction of oxazolone colitis." (PMID 30425718, 2018). "CD4+CD25− effector T cells from colitic Gαi2−/− mice (KO-Teff), or CD4+CD25− effector T cells from WT mice (WT-Teff) were transferred with or without CD4+CD25+ Treg from Gαi2−/− mice with colitis (KO-Treg) or WT mice (WT-Treg) at a 4∶1 Teff∶Treg ratio into RAG2−/− recipients." (PMID 21966415, 2011). "However, the same study also revealed that ITK is required for the suppressive function of Tregs in inflammatory diseases: In Rag1−/−, reconstituted with naïve CD4+ cells, a co-transfer of CD4+CD25+ cells, derived from ITKKO mice, could not prevent the development of colitis." (PMID 32808093, 2020).
colitis (continued). "Also, the absolute numbers of CD4+ T cells were significantly diminished within the MLN suggesting that at least to a certain degree hampered systemic T cell activation and expansion may account for the lack of a colitis-mediating T cell pool in the absence of T cell-extrinsic IRF4 expression." (PMID 33584655, 2020).